MMP2 (matrix metallopeptidase 2)
Diseases named in the same sentence as MMP2 in open-access papers (continued):
Sharing a sentence is not in itself a finding about the gene and the disease.
glioma (continued). "Furthermore, the CCL5‐induced invasion of glioma cells and the corresponding increase in MMP2 are suppressed when p‐CaMKII is inhibited." (PMID 40620486, 2025). "Moreover, upregulation of miR-760 expression suppressed MMP2 expression in glioma cells, while MMP2 upregulation enhanced glioma cell proliferation, migration, and invasion." (PMID 38706905, 2024). "Additionally, we investigated the molecular mechanism by which miR-760 influences glioma cell proliferation, migration, and invasion through MMP2 regulation." (PMID 38706905, 2024). "A previous study pointed out that SPARC could upregulate the expression of MT1-MMP in U87MG glioma cells and then affect the activation of MMP-2, thus promoting the invasion of glioma." (PMID 38388415, 2024). "Furthermore, an uptick in MMP2/9 was observed within the hsa-miR-134-5p mimic groups, suggesting an inhibition of glioma cell cycle progression influenced by hsa-miR-134-5p’s suppression of MMP2/MMP9." (PMID 38579169, 2024). "They observed a statistically significant association between MMP-2 expression in gliomas and tumor diameter as well as peritumoral edema, but not with sex, age, or tumor grade." (PMID 39684754, 2024). "Summing up, P129 could inhibit the invasion of glioma by suppressing MMP-2 and MMP-9 and EMT progression." (PMID 38184514, 2024). "The EdU assay produced comparable results to the CCK-8 assay, indicating that miR-760 overexpression decreased glioma cell growth and that this effect could be reversed by MMP2 overexpression plasmid transfection (p<0.01)." (PMID 38706905, 2024). "Additionally, MMP2 expression was greatly increased in glioma samples and was negatively correlated with miR-760 expression." (PMID 38706905, 2024). "MMP2 and MMP9 play important roles in GBM invasion and are associated with glioma malignancy." (PMID 38906916, 2024). "Overall, these data provide evidence that P129 could inhibit glioma cell metastasis via the downregulation of MMP-2 and MMP-9 and inhibition of EMT." (PMID 38184514, 2024). "While matrix metalloproteinases (MMPs) are metacin-like proteases that regulate tissue hemostasis and immunity, mammalian RTV-1 (a homolog of SmVAL9) has been shown to upregulate MMP-2 activity in glioma cells and control the growth, survival, and invasion of glioma cells." (PMID 39481080, 2024). "Although information about PEPD is limited, in several studies, the role of MMP-2 and MMP-9 has been underlined, e.g., finding positive correlations between MMPs levels and increasing grades of glioma malignancy associated with invasion, recurrences, poor prognosis, and shorter survival." (PMID 38275897, 2024). "It is not well known the impact that gliomas have on these ligand-gated channels, but they could potentially include a role in triggering matrix metalloproteinase 2 (MMP-2)." (PMID 37241023, 2023). "Additionally, a study by Sarkar and Yong showed that increases in IL-1β and TNF-α levels were positively correlated with glioma cell invasiveness and a corresponding elevation of MMP-2 and MMP-9 proteins." (PMID 36675073, 2023). "In support of the data, in vitro studies revealed that glioma cells tend to migrate, in a heterogeneous shape, toward activated microglia-conditioned media and that such migration is sustained through an overexpression of MMP-2." (PMID 36980765, 2023). "HMGA2 increases glioma cell migration in part by increasing MMP-2." (PMID 37370851, 2023). "Tozuleristide, also known as BLZ-100 or “Tumor Paint,” is a biconjugate of a derivative of chlorotoxin, a small protein that is thought to selectively bind to targets such as calpactin and MMP-2 that are clustered in lipid rafts on the surface of glioma cells and CG." (PMID 37193364, 2023). "Cholesterol depletion induces ANTXR2-dependent activation of MMP-2 in glioma cells." (PMID 38023262, 2023). "Many interventions can inhibit glioma growth by inhibiting the expression of MMP-2 and MMP-9." (PMID 37759283, 2023).
glioma (continued). "MMP-2 expression is positively correlated with glioma invasiveness and poor patient prognosis." (PMID 36969167, 2023). "However, TMEM176A negatively regulated cell invasion through reducing the expression of MMP-2/9 in different types of cancer such as glioma, esophageal, liver, and colorectal cancers." (PMID 37367036, 2023). "- Through PLD-1 suppression by QUE, glioma cell proliferation is achieved- QUE suppressed PLD1 expression through inhibition of NFkB transactivation- QUE inhibited tumor cell invasion by reducing MMP-2 activity." (PMID 36986827, 2023). "MMP-14, MMP-9, and MMP-2 induce matrix remodeling, which promotes VM in glioma." (PMID 36294763, 2022). "Aberrant MMP-2 and MMP-9 activities have been implicated in the deterioration of glioma." (PMID 35012441, 2022). "In addition to LRP1, glioma cells overexpress MMP-2 proteins with enzyme activity, which can also be exploited to increase CPP selectivity." (PMID 35631493, 2022). "We also analyzed the effect of SCIN and MMP2/9 on the prognosis of glioma in our clinical samples." (PMID 36291348, 2022). "Administration of THC inhibited MMP-2 expression in an in vivo model of glioma." (PMID 35011711, 2022). "Although multiple non-malignant cells, such as endothelial cells or macrophages, can secrete different isoforms of these proteases, glioma tissue has been shown to be one of the main sources of production of MMPs (mostly MMP-2 and MMP-9), as compared to normal brain tissue and other CNS tumors." (PMID 35631639, 2022). "Interestingly, THC treatment depressed TIMP-1 and MMP-2 expression in glioma cell lines as well as in cultured human GBM primary cells." (PMID 35454080, 2022). "After the extracellular overexpressed MMP2 degraded the MMP2-cleavable linker and exposed the R8, the micelles could successfully target the glioma cells and enter the tumor’s center." (PMID 36425579, 2022). "ADAMDEC1 was positively correlated with MMP2, and we predicted that ADAMDEC1 could regulate the proliferation and invasion of glioma cells by affecting the expression of MMP2." (PMID 36172139, 2022). "Moreover, Angiopoietin-2 (Ang-2) increases the secretion of matrix metalloproteinase-2 (MMP-2) favoring human glioma cells invasive capacity." (PMID 35433447, 2022). "In support of the importance of modulation of extracellular matrix proteolysis in anti-invasive cannabinoid action, other groups have demonstrated downregulation of MMP-2 by THC in glioma cells and downregulation of MMP-2 and -9 in HCC cells treated with CB1 (ACEA) or CB2 agonists (CB65)." (PMID 35277658, 2022). "In addition, the local administration of THC down-regulated TIMP-1 and MMP-2 expression in glioma-bearing mice and in two patients with recurrent GBM." (PMID 35454080, 2022). "Moreover, increases in expressions of MMP-9 and MMP-2 were indicative of a poor prognosis in glioma." (PMID 35884733, 2022). "Furthermore, gelatin zymography also confirmed that 0.2% Cs-SeNPs can inhibit cell migration and cell invasion of glioma cells via reducing MMP-2/9 activities." (PMID 35957037, 2022). "Finally, SCIN and MMP2/9 protein expression among different grades of glioma was performed and the results were obtained via immunohistochemistry and Western blot assays." (PMID 36291348, 2022). "MMP2 interacts with integrin and activates glioma invasiveness." (PMID 35448036, 2022). "Inhibition of p-CaMKII suppressed CCL5-mediated glioma invasion and upregulation of MMP2." (PMID 35600367, 2022). "Considering the important role of SCIN and MMP2/9 in the occurrence and development of a glioma, we speculate that the high expression of SCIN combined with MMP2/9 may enhance the invasiveness of gliomas and lead to a more malignant tumor progression." (PMID 36291348, 2022). "The correlations of mRNA expression between SCIN and MMP2/9 were analyzed by TCGA glioma." (PMID 36291348, 2022). "As we found, ADAMDEC1 had co-expression with MMP2 in gliomas." (PMID 36172139, 2022).
glioma (continued). "In the present study, SCIN has been identified as a new prognostic biomarker and associated with MMP2/9 expression and tumor immune infiltration in gliomas, which indicates that SCIN may be used as a target for glioma treatment." (PMID 36291348, 2022). "And chlorotoxin may inhibit cell migration and invasion by interacting with both Cl- channel proteins and MMP-2 in glioma cells." (PMID 36033489, 2022). "In our study, p-JNK and p-p65 were decreased as FABP6 was reduced, which may inhibit MMP-2 and cathepsin B expression in glioma." (PMID 34685761, 2021). "MMP-2 (gelatinase A) is a type IV collagenase that plays a vital role in glioma carcinogenesis." (PMID 34832965, 2021). "FOXM1 activates MMP2 to enhance the invasiveness of gliomas." (PMID 33423377, 2021). "Also, silencing MMP-2 in glioma cell lines impaired α5, β1 integrin, IL-6 signaling, and STAT3 phosphorylation, thus hindering the proliferation and growth of glioma." (PMID 33854965, 2021). "Additionally, we find that B7H3 is positively correlated with VEGFA and MMP2 by bioinformatics analysis in gliomas." (PMID 34079802, 2021). "STAT3 regulates the migration and invasion of glioma cells by targeting MMP2, MMP9, SNAIL, etc.." (PMID 34425834, 2021). "In human GBM, VEGFA, MMP-9, and MMP2 levels correlate with glioma progression and could be secreted by both tumour cells and MDSCs." (PMID 33452462, 2021). "FAK phosphorylation was reported to promote STAT3 activation and MMP-2 activity in gliomas." (PMID 33428595, 2021). "Besides, SLC39A1 promotes the proliferation of glioma cells, inhibits their apoptosis, and promotes the expression of MMP2 & MMP9." (PMID 34615436, 2021). "The current results indicate PTE may inhibit the migration and invasion of glioma cells via downregulation of MMP-2 and MMP-9 accompanied by EMT progression." (PMID 33737656, 2021). "In terms of possible mechanisms, early studies indicated that cannabinoids downregulate VEGF (vascular endothelial growth factor) and angiopoietin-2 (Ang-2) in mouse skin and glioma tumours, with additional inhibition of MMP-2 formation described in glioma tumours." (PMID 34830856, 2021). "Overall, the present data indicated that PTE may inhibit the migration and invasion of glioma cells via downregulation of MMP-2 and MMP-9 and EMT suppression." (PMID 33737656, 2021). "Our data suggest that elevation of PPFIBP1 expression in glioma leads to increased integrin α3, integrin α4, and integrin β8 and MMP-2 expression, along with enhanced cell migration and invasion via activation of FAK/Src/JNK signaling pathway, probably through interacting with SRCIN1." (PMID 34480020, 2021). "Upregulated endogenous TLR2 ligand versican was reported to induce the expression of membrane type 1 matrix-bound metalloproteinase (MT1-MMP) in GAMs which activates tumor-released MMP2 and of glioma cells, contributing to invasive and migratory behavior of glioma." (PMID 34715891, 2021). "The enhanced invasion may be mediated by an IL-6-induced increase in STAT3 signaling and upregulation of MMP2 in glioma cells." (PMID 34503065, 2021). "MMP-2 has shown multiple effects in tumor progression, and promoted glioma malignancies." (PMID 33718164, 2021). "VEGF/Akt/surviving and HIF-1α/MMP-2 pathways might be involved in canstatin-inhibited VM formation in U87 glioma cells." (PMID 34434564, 2021). "Therefore, we found that TSN inhibits tumor invasion and migration through decreased MMP-2/9 expression in human glioma cells." (PMID 34530814, 2021). "c-Cbl also upregulates the expression of MMP2, which results in promoted glioma invasion." (PMID 33466790, 2021). "However, more studies are needed to elucidate how MMP-9 and/or MMP-2 directly or indirectly affect glioma cell migration in patients." (PMID 32172480, 2021). "Compared with normal brain tissue, MMP-2 is highly expressed in gliomas." (PMID 33718164, 2021).
glioma (continued). "Functional experiments have shown that overexpression of miR-506 could inhibit the migration and invasion of glioma cells and reduce the protein expression levels of MMP2, cyclin D1 and Bcl-2." (PMID 34425834, 2021). "In addition, captopril was found to inhibit matrix metalloproteinase-2 (MMP-2), an enzyme that facilitates the rapid spread of gliomas through destroying type IV collagen, one of the structural elements of the extracellular matrix." (PMID 34944514, 2021). "The researchers concluded that MMP-2 and MT-MMPs might regulate glioma invasiveness, while MMP-9 plays a crucial role in angiogenesis within the tumor." (PMID 34638718, 2021). "We detected the expression of MMP2 and found that it decreased in sh‐linc00475 glioma cells." (PMID 33336871, 2021). "In glioma cells, high expressions of MMP2 and MMP9 suggest an enhanced VM formation ability." (PMID 33542193, 2021). "MMP-2 and MMP-9 are primarily associated with the invasiveness of high-grade gliomas, and MMP-2 activity in GBM was reported to be five-fold greater compared to normal brain or low-grade gliomas." (PMID 32545852, 2020). "MMP-2 inhibitor III suppressed the invasion of U251 cells in human glioma." (PMID 33553142, 2020). "MiR-526b-3p inhibited glioma angiogenesis via repressing MMP2 and VEGFA." (PMID 32600379, 2020). "In vitro experimental results show that SLC39A1 promotes the proliferation of glioma cells and inhibits their apoptosis, and may be related to MMP2\MMP9 up-regulation." (PMID 33292262, 2020). "The micelles could effectively target to the glioma cells and then further migrate into the center of the tumor after the MMP2-cleavable linker was degraded by the overexpressed extracellular MMP2, resulting in the exposure of R8." (PMID 32508641, 2020). "Indeed, Ang-2 stimulated invasion of glioma and breast cancer cells through up-regulation and activation of matrix metalloprotease 2 (MMP-2) in the tumor cells." (PMID 32085414, 2020). "Supernatants from U87 glioma cells, in contrast, contained more pro-MMP2 than active MMP2." (PMID 32872536, 2020). "Glioma lethality was rescued by MMP1 or MMP2 down regulation." (PMID 31846454, 2019). "Moreover, Ku’s study showed that YKL-40 affected glioma cell invasion through regulation of MMP-2 expression, adhesion to ECM, cytoskeleton rearrangement and contractility." (PMID 31624472, 2019). "Our results show that an Akt/MMP2/MMP9 axis potentially regulates VM formation in glioma." (PMID 31754182, 2019). "We investigated whether TNC impaired VM formation in glioma cells upon a reduction in Akt phosphorylation and MMP2/9 downregulation." (PMID 31754182, 2019). "For instance, the theranostic 131I-labeled PAMAM dendrimers modified with PEG and chlorotoxin (CTX) as the targeting agent were employed for targeted SPECT imaging and radiotherapy of a matrix metalloproteinase-2 (MMP-2) overexpressing xenografted glioma model in vivo." (PMID 31434562, 2019). "In glioma tissues, MMP-2 and MMP-9 are the two MMPs most highly expressed." (PMID 31551765, 2019). "Furthermore, the immunofluorescence image showed that the MMP-2 expression in C6 glioma cells and the western blot analysis showed that MMP-2 was upregulated in the tumor compared with normal brain parenchyma." (PMID 30670934, 2018). "In accordance with this effect, we also found that CXCL16 stimulation increased the expression level of the matrix metalloproteinases mmp9 and mmp2 (n = 6, p < 0.05; Student's t-test), whose activity is reported to be involved with the invasion ability of glioma cells." (PMID 30542347, 2018). "In a study on the effects of radiotherapy on gliomas, Park found that radiation switched on the EGFR-mediated p38/Akt and PI3K/Akt signaling pathways, which led to increased glioma cell metastasis and invasive ability by up-regulating matrix metalloproteinase 2 (MMP-2) expressions." (PMID 29958545, 2018). "Increased MMP-2 expression is related to the tissue invasion capacity of glioma cells." (PMID 30486274, 2018).
glioma (continued). "To investigate whether the correlations between HMGA2 and MMP2 exist in human glioma tissues, we further detected MMP2 in our FFPE specimens by IHC and compared its expression pattern with that of HMGA2." (PMID 29733521, 2018). "Irradiation-enhanced MMP2 promoter activity, mRNA transcription, and protein secretion associated with invasiveness was observed in glioma cells lacking functional PTEN (U87, U251, U373, and C6) but not in those harboring wild-type PTEN (LN18 and LN428)." (PMID 30134800, 2018). "Furthermore, the expression of membrane type 1-matrix metalloproteinase 1 (MT1-MMP), which is necessary to activate pro-MMP-2, increases with glioma grade." (PMID 29389898, 2018). "Two studies reported the association between MMP-2/TIMP-2 and the WHO grade of gliomas." (PMID 26729052, 2017). "Importantly, overexpression of FoxR2 promotes glioma cell proliferation and invasion through decreasing p27 expression and increasing MMP-2 expression." (PMID 28915588, 2017). "It has been shown that resveratrol may decrease the expression levels of MMP-2 through inhibiting the activity of NF-κB and subsequently reducing the invasion of glioma." (PMID 28512471, 2017). "As reported, aberrant over-expression of Sp1 in human glioma promoted MMP2-mediated cell invasion." (PMID 29262634, 2017). "And, MMP-2/TIMP-2 rose with the increase of glioma grade, which may be used as criteria of WHO grade in gliomas." (PMID 26729052, 2017). "MMP-2/TIMP-2 testing may predict the WHO grade of gliomas, and MMP-2 expression may serve as a biomarker for the prognosis of patients with gliomas, which required to be further certified by future studies." (PMID 26729052, 2017). "Based on these knowledge,we speculated that SH3GL2 might negatively regulate STAT3 which would affect the expression of MMP2 in human glioma cells." (PMID 28470949, 2017). "Moreover, from a search of available microarray data (PrognoScan database), our previously study observed that MMP-2 has been negatively correlated with the overall survival rate of patients with glioma." (PMID 29285298, 2017). "MMP-9 and MMP-2 are important matrix metalloproteinases in the migration of glioma cells." (PMID 29062841, 2017). "It was found that MMP-2 expression in patients with high-grade gliomas was significantly higher than that in patients with low-grade gliomas (n = 24, OR = 6.54, CI = 4.98–8.60), and there was no significant heterogeneity in the meta-analysis (I2 = 0 %, P = 0.911)." (PMID 26729052, 2017). "For the well-known pro-invasive role of MMP2 in cancer, its favorable prognostic effect in low-median grades of glioma may be related to a better survival of glioma with more invasive tumor cells than that with more proliferative tumor cells." (PMID 29113349, 2017). "In addition, the protein levels of MMP-2 and N-Cadherin were reduced in glioma cells treated with DHA." (PMID 28208619, 2017). "Finally, 25 studies were included in the meta-analysis, of which 24 studies were related to MMP-2 and gliomas and seven studies for TIMP-2 and gliomas." (PMID 26729052, 2017). "Moreover, glioma cells express various MMPs, among which MMP-2 is supposed to most effectively degrade ECM components." (PMID 29285298, 2017). "Moreover, miRNA-29c was significantly downregulated in glioma cells and tissues, and inhibits glioma cell proliferation, migration, invasion and angiogenesis via targeting MMP-2 and downregulating VEGF." (PMID 27895048, 2017). "Similarly, our study results revealed that MMP-2 was highly secreted by GBM cells, and overexpression of MMP-2 has been found in clinical specimens and to be correlated with tumor invasion in gliomas." (PMID 29285298, 2017). "Some studies have also showed the expression of MMP-2 in human gliomas." (PMID 27051552, 2016). "Moreover, previous study indicates that FOXM1 directly binds to and activates the promoter of the MMP2 gene in glioma cells." (PMID 27034162, 2016).